NAPRT (nicotinate phosphoribosyltransferase)
Diseases named in the same sentence as NAPRT in open-access papers (continued):
Sharing a sentence is not in itself a finding about the gene and the disease.
tumor (39 papers, 2014 to 2025). "This treatment approach was indeed successful in several NAPRT-deficient tumor models, expanding the therapeutic window of NAMPT inhibitors and mitigating toxicity." (PMID 38396769, 2024). "We have previously identified NAPRT variants in predicted splicing sites, thus, we further screened several tumor cell lines for mutations." (PMID 26675378, 2016). "Thus, further studies are required to confirm the usefulness of a combined NAMPT inhibitor plus NA as a treatment for NAPRT-deficient neoplasms." (PMID 38396769, 2024). "Therefore, the coadministration of NA and NAMPT inhibitors has been proposed as a new therapeutic strategy, but only in tumours deficient in NAPRT." (PMID 36078035, 2022). "Whether tumor cells depend more on NAMPT or NAPRT is associated with the normal tissue from which the tumor originates, which was mentioned in the previous paper." (PMID 35906622, 2022). "However, in other experiments, the in vivo antitumor effects of the NAMPT inhibitors, GNE-617 and GNE-618, were found to be abrogated by NA supplementation even in the xenografts of NAPRT-deficient cell lines and patient-derived xenograft tumor models." (PMID 34068917, 2021). "Similarly, despite search efforts, there are no genetic mutations predicted to give rise to functionally inactive NAPRT protein in tumor cells." (PMID 29100430, 2017). "Therefore, a highly specific and sensitive antibody against NAPRT protein such as 3C6D2 may be better suited for predicting susceptibility of tumor tissue to the niacin/NAMPTi combination in complex and heterogeneous patient tumor samples." (PMID 29100430, 2017). "The targeting of NAD + biosynthetic pathways with the inhibitors of nicotinamide phosphoribosyltransferase (NAMPT) or nicotinate phosphoribosyltransferase (NAPRT) showed anti-tumor effects and exerted sensitization to docetaxel in xenograft mice." (PMID 37453969, 2023). "In both cell lines, the coadministration of NAMPT and NAPRT inhibitors cooperated inhibiting tumor growth." (PMID 36864434, 2023). "The Detroit-562 line presents amplifications of the NAPRT gene (cbioportal.org/); thus, we assume that the line comes from a NAPRT-positive tumor, whose original tissue had high levels of NAPRT54−56." (PMID 36864434, 2023). "We observed that coadministration of the NAMPT inhibitor with the NAPRT inhibitor cooperated inhibiting tumor growth." (PMID 36864434, 2023). "Accordingly, coupling FK866 therapy to our NAPRT inhibitors would presumably reverse the protective effect of the intestinal bacteria and restore the anti-tumor effect of NAMPT inhibitors in vivo." (PMID 35890147, 2022). "Altogether, our study lays the background for further studies of these new NAPRT inhibitors, including in vivo testing in mouse tumor models and further drug optimization steps." (PMID 35890147, 2022). "NAPRT displays marked tissue and tumor specificity in terms of expression and its regulation mechanisms and is mostly present in several catabolic healthy mammalian tissues including the heart, kidney, liver, and small intestine." (PMID 35890155, 2022). "Specifically, our data strongly suggest that two conditions are required for gut bacteria to protect tumor cells from APO866-induced cell death: 1) the expression of NAPRT and 2) the availability of sufficient amounts of NAM to bacteria." (PMID 35396381, 2022). "Several studies indicated that the therapeutic activity of NAMPT inhibitors is largely dictated by the NAPRT expression status of the tumor cells." (PMID 35890147, 2022). "Development of novel NAPRTi, to obtain complete depletion of NAD in tumor insensitive to NAMPTi due to the overexpression of NAPRT should also be considered." (PMID 32266141, 2020). "The proportion of NAPRT positively staining cells within tumor sections across multiple samples is summarized according to tumor sub-type of lung or brain tumors." (PMID 29100430, 2017).
tumor (continued). "In the evaluation of tumor samples, cells were scored positive for NAPRT when either nuclear or cytosolic staining was observed; often, the staining appeared as both nuclear and cytosolic." (PMID 29100430, 2017). "Accurately predicting functional NAPRT expression in tumor cells will therefore be crucial for the selection of patients for this combination strategy." (PMID 29100430, 2017). "Overall, we demonstrate that NAMPT and NAPRT are ubiquitously expressed in normal human tissues, and we have detected novel NAPRT transcripts, in normal tissues and in tumor cell lines." (PMID 26675378, 2016). "In tumor cell lines, we found that the NAPRT gene is more widely expressed than expected, at the mRNA level, considering that several cell lines are negative for the protein." (PMID 26675378, 2016). "In addition to known tumor-promoting genes, e.g., c-MYC, YAP1, RAD51B, TRIB3, SLC17A9, JADE1, we found that NAPRT, encoding a key enzyme for NAD+ biosynthesis from nicotinic acid, was also suppressed in HCC cells by the BRD4 inhibitor." (PMID 35399501, 2022). "Silencing NAPRT in tumor cells could restore the therapeutic efficacy of NAMPT inhibitors even in the presence of bacteria and NAM." (PMID 35396381, 2022). "In tumours with high levels of NAPRT, tumour cells may have a better supply of NAD+, which allows for the activation of NAD+-dependent enzymes, including PARP1, which are required to protect against DNA damage and oxidative stress." (PMID 36078035, 2022). "Thus, tumours from tissues with high NAPRT expression will have higher NAPRT amplification, and conversely, tumours from tissues with low NAPRT expression will be dependent on NAMPT activity." (PMID 36078035, 2022). "However, the inhibitory effect was suppressed in NAPRT-positive tumours, that is, tumours that overexpressed this enzyme." (PMID 36078035, 2022). "While none of the cell lines expressed NAPRT, there was a strong expression of NAPRT in the tumor tissues from PDXs, independent of IDH1-mutation status." (PMID 31888244, 2019). "Based on our observations that mutant PPM1D blocks this pathway via tumor-specific NAPRT silencing, NA supplementation may be an effective approach to further enhance the therapeutic index associated with NAMPT inhibition." (PMID 31439867, 2019). "In addition, the proportion of tumor cells within the tumor field of view was scored as a percentage and grouped into categories: 0-10 %, 11-90 % or 91-100 % NAPRT positive and is illustrated graphically." (PMID 29100430, 2017). "Successful implementation of the strategy to widen the therapeutic index of NAMPT inhibitors by co-administration with niacin, will depend on the ability to correctly detect functional NAPRT in tumor tissue and on the ability of normal tissue to be protected by niacin administration." (PMID 29100430, 2017). "Additionally, because DNA methylation was recently established as a mechanism to suppress NAPRT gene expression, we evaluated the methylation status of the NAPRT promoter region in tumor cell lines." (PMID 26675378, 2016). "In particular, evidence on how is NAPRT expression regulated in tumor cells could spark developments to expand the use of NA cytoprotective therapies in treatments using NAMPT inhibitors." (PMID 26675378, 2016). "Additionally, in order to assess whether the catalytic function of NAPRT is essential, we tested the effect of the potent NAPRT inhibitor 2-hydroxynicotinic acid (2-HNA) on the nicotinaldehyde tumor-protective function against APO866." (PMID 36765744, 2023). "Furthermore, promoter methylation of NAPRT gene decreases as tumor advances." (PMID 31448236, 2019). "Therefore, one potential strategy to widen the therapeutic index of NAMPTis is to protect NAPRT positive healthy tissue but not NAPRT deficient tumor tissue by niacin co-administration." (PMID 29100430, 2017).
tumor (continued). "Expression of NAMPT, NAPRT, NT5E and QPRT were quantified by qPCR and Western blot in both established and primary GBM cell lines, and IHC was performed on sections from GBM tumours for the same proteins." (PMID 38893173, 2024). "Rather, NFD strongly synergized with NAMPTi, even against NAPRT-KO tumors, excluding the possibility that NFD effects are related to a tumor’s NA-metabolizing ability." (PMID 38092728, 2023). "In conclusion, the coinhibition of NAMPT and NAPRT improved the efficacy of antitumor treatment, indicating that the reduction in the NAD pool is important to prevent tumor growth." (PMID 36864434, 2023). "Previous studies found that high protein levels of NAPRT conferred resistance to NAMPT inhibition in several tumor types whereas the simultaneous blockade of NAMPT and NAPRT results in marked anti-tumor effects." (PMID 35890155, 2022). "Any therapeutic strategy aiming to block only one route of NAD+ biosynthesis should therefore be expected to fail in tumor cells in which the enzymatic apparatus of both NAD+ production routes (via NAMPT and via NAPRT) is expressed." (PMID 35396381, 2022). "In the past, NAMPT inhibitors (NAMPTi) showed modest anti-tumor activity mostly because NAMPT block was bypassed by compensation through other NAD-biosynthetic pathways, such as that regulated through NAPRT and NRK." (PMID 33419372, 2020). "Importantly, our results indicate that tumor infiltrating lymphocytes and other inflammatory cells stain NAPRT positive in the tumor samples examined, indicating that the niacin/NAMPTi combination could be compatible with immuno-oncology therapies such as the recently approved checkpoint inhibitors." (PMID 29100430, 2017). "Here, we describe our results of a global study of NAPRT and NAMPT expression across human tissues and tumor cell lines." (PMID 26675378, 2016). "Herein, we provide a comprehensive study of NAPRT and NAMPT expression across human tissues and tumor cell lines." (PMID 26675378, 2016). "Finally, the inhibition of both NAMPT and NAPRT improved the efficiency of the treatment, indicating that the reduction of the NAD pool is important for preventing tumor growth." (PMID 36864434, 2023). "Collectively, these data indicate that circulating NAR is derived from dietary NA NAPRT-dependently and that the NA-to-NAR conversion may limit the therapeutic anti-tumor efficacy of NAMPTi." (PMID 38092728, 2023). "Comparing the pattern of expression of the NAPRT and NAMPT genes in human tumour cells with nontumor cells, there is high variability in the levels of NAPRT mRNA and protein in tumour cells." (PMID 36078035, 2022). "This gives rise to the possibility of using a quantitative methylation-specific PCR method to predict lack of NAPRT expression in tumor tissue." (PMID 29100430, 2017). "To accurately evaluate the lack of NAPRT expression in primary tumor tissue while distinguishing it from surrounding normal tissue and endothelial tissue, we examined FFPE samples by IHC." (PMID 29100430, 2017). "The 3C6D2 antibody detected NAPRT in patient derived primary tumor sections and clearly distinguishes positive and negative staining areas." (PMID 29100430, 2017). "Given the absence of NAPRT expression in some tumor cell lines, we considered the occurrence of DNA cytosine methylation in the promoter region as previously suggested." (PMID 26675378, 2016). "When extrapolating these findings to the in vivo situation, we expect that the magnitude of effects of FK866 will be dependent on a tumor-cell’s nutrient state and its capacity for NAD+ synthesis via different metabolic pathways (i.e. via de novo or salvage pathways, via NAPRT or NAMPT)." (PMID 24824795, 2014). "This indicates that NAPRT might not be expressed by the tumor cells but by the normal surrounding tissue (e.g., endothelial cells)." (PMID 31888244, 2019).
tumor (continued). "Acid and niacin phosphoribosyl transferase (NAPRT) produce nicotinic acid mononucleotide (NAMN), which is then converted to nicotinic acid-adenine dinucleotide (NAAD) by NAMN transferase (NMNAT), where the salvage synthetic pathway is the primary source of energy for tumor cells." (PMID 31817697, 2019). "In contrast to cultured cells, we found a strong expression of NAPRT in tissue samples from xenografts, which might be explained by the presence of residual non-glial cells within the tumor tissue." (PMID 31888244, 2019). "Of note, within the NAPRT negative staining classification in all tumor types, 90 % of tumor samples were homogeneously NAPRT negative and only 10 % of this subgroup had heterogeneously staining tumors with infrequent NAPRT positive cells (ie 1-10 % of the tumor cells NAPRT positive)." (PMID 29100430, 2017). "However, in patient tumor tissue samples, it is not clear whether promoter methylation will consistently suppresses NAPRT protein expression sufficiently to prevent niacin rescue." (PMID 29100430, 2017). "Furthermore, unlike tumor cells, which mostly depend on NAMPT, normal cells can synthesize NAD+ through other biosynthetic pathways, such as nicotinic acid phosphoribosyltransferase (NAPRT)." (PMID 38448544, 2024). "Furthermore, in agreement with these authors, we showed that MM is a type of tumor completely addicted to NAMPT, without significant amplification of NAPRT, as reported in other tumors." (PMID 35272691, 2022).
infection (2 papers, 2022 to 2023). The state of being infected such as from the introduction of a foreign agent such as serum, vaccine, antigenic substance or organism. "Up-modulation was specific for NAMPT, while the other three NBEs, i.e., NAPRT, NMRK1, and QPRT, were unaffected by infection with BRAF V600E (heatmaps on the right)." (PMID 35272691, 2022).
adenocarcinoma (1 paper, 2022). A common cancer characterized by the presence of malignant glandular cells. "To conclude, our comprehensive analyses identified PTP4A3, NAPRT, and RECQL4 were co-amplified and co-expressed specifically in LEP/MIP adenocarcinoma, and RECQL4 was upregulated in the MIP group." (PMID 35992814, 2022).
metabolic disorders (1 paper, 2022). "More importantly, FK866 and quercetin consistently corrected NAD+ metabolic disorders, including expressions of NMNAT1, NAPRT, and NAMPT as well as NAD+ and NAD+/NADH levels both in vitro and in vivo." (PMID 35408818, 2022).
NAPRT also shares sentences with these, for which no sentence is quoted: lymphoma (4 papers); peripheral neuropathy (2); sarcoma (2); allergic disease (1); astrocytoma (1); bone marrow failure (1); dyslipidemia (1); hematological malignancies (1); hepatocellular carcinoma (1); immune disease (1); inflammatory bowel disease (1); multiple myeloma (1); myeloid malignancies (1); neuropathy (1); Obesity (1); ovarian tumors (1); prostate carcinoma (1); rectal cancer (1); schizophrenia (1); small cell lung carcinoma (1); steatosis (1); uveal melanoma (1).